S100A9 (S100 calcium binding protein A9)
Description:
S100A9 is a calcium- and zinc-binding protein which plays a prominent role in the regulation of inflammatory processes and immune response. It can induce neutrophil chemotaxis, adhesion, can increase the bactericidal activity of neutrophils by promoting phagocytosis via activation of SYK, PI3K/AKT, and ERK1/2 and can induce degranulation of neutrophils by a MAPK-dependent mechanism. Predominantly found as calprotectin (S100A8/A9) which has a wide plethora of intra- and extracellular functions. The intracellular functions include: facilitating leukocyte arachidonic acid trafficking and metabolism, modulation of the tubulin-dependent cytoskeleton during migration of phagocytes and activation of the neutrophilic NADPH-oxidase. Also participates in regulatory T-cell differentiation together with CD69. Activates NADPH-oxidase by facilitating the enzyme complex assembly at the cell membrane, transferring arachidonic acid, an essential cofactor, to the enzyme complex and S100A8 contributes to the enzyme assembly by directly binding to NCF2/P67PHOX. The extracellular functions involve pro-inflammatory, antimicrobial, oxidant-scavenging and apoptosis-inducing activities. Its pro-inflammatory activity includes recruitment of leukocytes, promotion of cytokine and chemokine production, and regulation of leukocyte adhesion and migration. Acts as an alarmin or a danger associated molecular pattern (DAMP) molecule and stimulates innate immune cells via binding to pattern recognition receptors such as Toll-like receptor 4 (TLR4) and receptor for advanced glycation endproducts (AGER). Binding to TLR4 and AGER activates the MAP-kinase and NF-kappa-B signaling pathways resulting in the amplification of the pro-inflammatory cascade. Has antimicrobial activity towards bacteria and fungi and exerts its antimicrobial activity probably via chelation of Zn(2+) which is essential for microbial growth. Can induce cell death via autophagy and apoptosis and this occurs through the cross-talk of mitochondria and lysosomes via reactive oxygen species (ROS) and the process involves BNIP3. Can regulate neutrophil number and apoptosis by an anti-apoptotic effect; regulates cell survival via ITGAM/ITGB and TLR4 and a signaling mechanism involving MEK-ERK. Its role as an oxidant scavenger has a protective role in preventing exaggerated tissue damage by scavenging oxidants. Can act as a potent amplifier of inflammation in autoimmunity as well as in cancer development and tumor spread. Has transnitrosylase activity; in oxidatively-modified low-densitity lipoprotein (LDL(ox))- induced S-nitrosylation of GAPDH on 'Cys-247' proposed to transfer the NO moiety from NOS2/iNOS to GAPDH via its own S-nitrosylated Cys-3. The iNOS-S100A8/A9 transnitrosylase complex is proposed to also direct selective inflammatory stimulus-dependent S-nitrosylation of multiple targets such as ANXA5, EZR, MSN and VIM by recognizing a [IL]-x-C-x-x-[DE] motif.
Synonyms: MRP-14; p14; CAGB; CFAG; MRP14; MIF; NIF; LIAG; MAC387; 60B8AG; CGLB; S100-A9; L1AG
Tractability: Small molecule: a structure with a bound ligand is known; a high-quality ligand is known. Antibody: UniProt places it where antibodies can reach, with high confidence; its Gene Ontology location is reachable by antibodies, with high confidence; the Human Protein Atlas places it where antibodies can reach. PROTAC: its protein half-life has been measured; a small molecule that binds it is known.
Gene: Protein-coding gene on chromosome 1 (153,357,767 to 153,361,027, forward strand). Ensembl gene ENSG00000163220.
Subcellular location: Secreted; Cytoplasm; Cytoplasm, cytoskeleton; Cell membrane
Subcellular location (Human Protein Atlas): Cytosol; Intermediate filaments; Plasma membrane; Predicted to be secreted
Pathways (Reactome):
Immune System: ER-Phagosome pathway; Metal sequestration by antimicrobial proteins; MyD88:MAL(TIRAP) cascade initiated on plasma membrane; Neutrophil degranulation; Regulation of TLR by endogenous ligand
Disease: IRAK4 deficiency (TLR2/4); MyD88 deficiency (TLR2/4)
Signal Transduction: RHO GTPases Activate NADPH Oxidases
Vesicle-mediated transport: Scavenging by Class B Receptors
Gene Ontology:
Molecular function: protein binding; arachidonate binding; calcium ion binding; calcium-dependent protein binding; microtubule binding; RAGE receptor binding; Toll-like receptor 4 binding; zinc ion binding
Biological process: antimicrobial humoral immune response mediated by antimicrobial peptide; autophagy; leukocyte migration involved in inflammatory response; neutrophil aggregation; neutrophil chemotaxis; peptidyl-cysteine S-trans-nitrosylation; positive regulation of inflammatory response; positive regulation of intrinsic apoptotic signaling pathway; astrocyte development; autocrine signaling; cell-cell signaling; chronic inflammatory response; defense response to bacterium; defense response to fungus; endothelial cell migration; inflammatory response; positive regulation of cell growth; positive regulation of neuron projection development; regulation of cytoskeleton organization; regulation of respiratory burst involved in inflammatory response; regulation of toll-like receptor signaling pathway
Cellular component: calprotectin complex; cytoplasm; cytosol; extracellular exosome; extracellular matrix; extracellular region; intermediate filament cytoskeleton; nucleus; plasma membrane; S100A9 complex; cytoskeleton; secretory granule lumen
Genetic constraint (gnomAD): Loss-of-function variants: 2 observed, 4.09 expected, observed/expected ratio (o/e) 0.49, 90% interval 0.2 to 1.47. That is too few expected variants to judge how well the gene tolerates losing a copy. Missense variants: 130 observed, 148.4 expected, observed/expected ratio (o/e) 0.88, 90% interval 0.76 to 1.01. Synonymous variants: 67 observed, 56.32 expected, observed/expected ratio (o/e) 1.19, 90% interval 0.98 to 1.46.
Homologues: Orthologues: chimpanzee S100A9 (99% identical), macaque S100A9 (89% identical), rabbit S100A9 (67% identical), dog S100A9 (64% identical), guinea pig S100A9 (62% identical), rat S100a9 (60% identical), mouse S100a9 (56% identical), mouse Gm5849 (43% identical), mouse Gm63953 (42% identical), mouse Gm63964 (39% identical), zebrafish s100s (32% identical), zebrafish s100t (30% identical), and 2 more. Paralogues in human: S100A12 (38% identical), S100B (32% identical), S100P (30% identical), S100A1 (29% identical), S100A11 (29% identical), S100Z (29% identical), S100A2 (27% identical), S100A3 (26% identical), S100A10 (25% identical), S100A13 (25% identical), S100A4 (25% identical), S100A5 (25% identical), and 9 more.
Diseases named in the same sentence as S100A9 in open-access papers:
S100A9 is named in the same sentence as 473 diseases in open-access papers, as found by Europe PMC text mining. Sharing a sentence is not in itself a finding about the gene and the disease. The quoted sentences say what the papers report.
psoriasis (120 papers, 2005 to 2026). An autoimmune condition characterized by red, well-delineated plaques with silvery scales that are usually on the extensor surfaces and scalp. "Further examination of gene signature in KCs indicated decreased expression of various psoriasis hallmark genes, such as S100a8, S100a9 and Cxcl1 in K14Cre/+Lztr1fl/fl KCs compared to Lztr1fl/fl KCs." (PMID 41162356, 2025). "Using the IMQ-induced psoriasis model, we found that Aim2 deficiency reduces mRNA expression of the KC markers Lcn2, Krt14, and S100a9." (PMID 39352743, 2024). "S100A9 overexpression was also reported to be associated with other skin diseases, such as psoriasis." (PMID 37936894, 2023). "S100A9-specific deficient mice show decreased psoriasis-like skin inflammation caused by imiquimod, which is associated with increased psoriasis-associated inflammatory cytokine production in the skin." (PMID 37891988, 2023). "The network pharmacology results revealed that the key targets of active STT components, namely GM2A, REN, MMP12, RBP4, and S100A9, are primarily associated with psoriasis, potentially serving as the basis for the therapeutic effectiveness of STT." (PMID 37653756, 2023). "Surprisingly, S100A9-deficient mice show slight decreases in the response of neutrophils to stimulation with chemoattractant and slight aggravation of psoriasis symptoms compared with control mice, indicating functional differences between S100A8 and S100A9." (PMID 37346040, 2023). "Their study revealed that the topical application of compound 3 (2 mM) significantly ameliorated hyperplasia and inflammatory cell infiltration and suppressed the expression of the psoriasis-associated genes S100a9, Krt1, Il17a, and Il22." (PMID 37111813, 2023). "In turn, psoriasis-associated inflammatory markers, such as IL-1b, hBD2 and S100A9, were significantly upregulated in the psoriatic skin model at both mRNA and protein levels." (PMID 35745784, 2022). "Accordingly, genes associated with psoriasis, including S100a8, S100a9, Camp, Tnf, Il1b, Il23a, and Ccl2, were strongly downregulated." (PMID 35869084, 2022). "In our study, S100A7, S100A8 and S100A9 were significantly involved in the IL-17A pathway, which is strongly implicated in psoriasis pathogenesis." (PMID 36483564, 2022). "Expression and secretion of two pro-inflammatory molecules of the S100-alarmin family, S100A8 and S100A9, in keratinocytes is a hallmark of psoriasis, which is also characterized by an altered differentiation of keratinocytes." (PMID 33643287, 2020). "S100A7, S100A8 and S100A9, calcium-binding proteins, are located in the psoriasis susceptibility locus 4 and are highly expressed at the epidermis of psoriasis skin lesions." (PMID 32194991, 2020). "We found that, upon IL-36 stimulation, IκBζ was actively recruited to the promoter regions of its target genes, including genes encoding for the chemokines Csf3, Cxcl1, and Cxcl2 and the psoriasis-associated antimicrobial proteins Defb4 and S100a9." (PMID 31622280, 2019). "The genes coding for S100A8 and S100A9 are located within the psoriasis susceptibility locus 4 (PSORS4) mapped to chromosome 1q21." (PMID 30865695, 2019). "These include S100a7a (psoriasin) and S100a9, both encoding antimicrobial and/or chemotactic proteins which are expressed under a variety of epidermal insults including psoriasis and wound healing." (PMID 29378633, 2018). "S100a8 and S100a9, which encodes a calcium-binding protein also known as calprotectin, an early biomarker of psoriasis, were among the most up-regulated genes." (PMID 29158586, 2017). "Skin tissues of JunB/c-Jun double-mutant (DKO) mice show elevated levels of S100A9 proteins, and in humans genes encoding these proteins are localized in the psoriasis susceptibility region PSORS410." (PMID 27698489, 2016). "Epidermal expression of S100A8 and S100A9 is a hallmark of psoriasis." (PMID 35812457, 2022).
psoriasis (continued). "The expression of many genes known to be associated with psoriasis, including Lce3f, Sprr2b, Krt15, S100a8, S100a9, Il17a, Il17f, Il18, Il20, Il22, and Ccl20, was downregulated in the skin of IMQ-treated Camk4−/− mice compared with those of IMQ-treated Camk4+/+ mice." (PMID 35869084, 2022). "After consulting the literature, we found that in psoriasis and cancer diseases, the IL-17 signaling pathway can cause the production of pro-inflammatory factors such as S100a8 and S100a9, thereby promoting the generation of inflammation and the metastasis of cancer cells." (PMID 35741040, 2022). "Importantly, CXCL9 and SPRR1B, as well as methylation markers TGM6 and S100A9, have an impact on the risk of psoriasis." (PMID 34134787, 2021). "In addition, mRNA expression of the psoriasis-associated genes Il17a, Tnfa, S100a9, Il17c and Il1f9 was induced by tamoxifen in the ears and the back skin." (PMID 32597759, 2020). "In addition, expression of proteins, such as S100A9 and S100A9, associated with regeneration of epidermal keratinocytes also functions as chemotactic factors for neutrophils in psoriasis." (PMID 29232931, 2017). "WY14643 treatment significantly downregulated psoriasis‐associated inflammatory cytokines and chemokines (Il17a, Il1b, Cxcl1, Cxcl2, Cxcl3, Cxcl15, and Csf3) as well as the antimicrobial peptides S100a8 and S100a9 in IMQ‐induced skin lesions at the transcriptional level." (PMID 40878384, 2025). "Nomogram showed that TGM6 and S100A9 may be associated with an increased risk of psoriasis." (PMID 34134787, 2021). "Among others, important psoriasis-associated target genes of IκBζ include certain chemo- and cytokines (e.g., Cxcl1, Cxcl2, Cxcl5, Ccl3, and Il17c) as well as antimicrobial proteins, such as S100 calcium-binding proteins (e.g., S100a9), β-defensin-2 (Defb4), and lipocalin-2 (Lcn2)." (PMID 31622280, 2019). "Therefore, we asked whether S100A9 loss would alter psoriasis-like skin phenotypes in K14-Angptl6 Tg mice by genetically deleting S100a9 in K14-Angptl6 Tg mice (K14-Angptl6 Tg;S100a9−/−) using CRISPR-Cas9-mediated technology." (PMID 27698489, 2016). "The heatmap analysis highlighted similarities in the regulation of gene expression between ST-IMQ treatment, LT-IMQ treatment and human psoriasis (e.g. S100A9, BD3 or IL-17 A)." (PMID 40702143, 2025). "In contrast, both S100A8 and S100A9 are significantly increased in the serum and damaged skin of psoriasis patients." (PMID 38255845, 2024). "We analyzed ScRNA-seq dataset GSE162183 from Gao’s study and found that both S100A8 and S100A9 were among the top 10 molecules expressed in lesional skin tissue of psoriasis patients, with notably high expression in keratinocytes." (PMID 38429278, 2024). "The expression of S100a8 and S100a9 was increased in IMQ-induced psoriasis both in bulk RNA-seq and scRNA-seq." (PMID 38472183, 2024). "Knocking out S100A9 in a psoriasis mouse model strongly attenuated psoriasiform skin disease and inflammation, with reduced C3 volume and mild immune infiltration." (PMID 38255845, 2024). "Among them, the expression of IL17A is predominant in psoriasis skin lesions, and IL-17 increases the secretion of antimicrobial peptides (Defb4, Lcn2, S100a7, and S100a9) by keratinocytes." (PMID 37649889, 2023). "Psoriasis severity is associated with S100A8 expression; moreover, S100A9 is highly expressed in psoriatic skin lesions." (PMID 37891988, 2023). "The network pharmacology results revealed that the primary targets of the active ingredients in STT were S100A9, GM2A, REN, MMP12, and RBP4, all of which were primarily associated with psoriasis." (PMID 37653756, 2023). "S100A7, S100A8, and S100A9 were markedly over-expressed in all three layers in PP, consistent with previous psoriasis studies." (PMID 37308489, 2023). "Expression levels of S100A8 and S100A9 are significantly elevated in psoriatic keratinocytes and leukocytes, and their expression levels correlate positively with the severity of psoriasis." (PMID 37346040, 2023).
psoriasis (continued). "To examine the anti-inflammatory effect of AOA on psoriasis, we observed changes in the expression of antimicrobial peptides, such as defensin β 4 (Defb4), lipocalin 2 (Lcn2), S100a7, and S100a9, which are known to amplify local inflammatory processes." (PMID 37649889, 2023). "Global or skin-specific transgenic mice overexpressing mouse sPLA2-IIF (Pla2g2f-TG) spontaneously develop psoriasis-like epidermal hyperplasia and alopecia, with increased expression of a panel of psoriasis markers, including S100A9 and IL-36α." (PMID 37189415, 2023). "Analysis of the genome-wide transcription pattern of monocytes revealed IL6 as the top gene induced by S100 alarmin stimulation via interaction with TLR4, and targeted deletion of S100A9 ameliorated inflammation in a murine psoriasis model." (PMID 35543413, 2022). "S100A8 and S100A9 are thought to be characteristic of several acute and chronic inflammatory disease, including psoriasis, inflammatory bowel disease, and rheumatoid arthritis." (PMID 34934042, 2021). "Animal experiments have demonstrated that psoriasiform dermatitis was significantly alleviated and a marked reduction in C3 has been observed throughout when the S100A9 gene was deleted, in an imiquimod-induced mouse psoriasis model." (PMID 33959184, 2021). "During dermal inflammation or wound healing complexes of S100A8 and S100A9 are expressed and released by keratinocytes and activated leukocytes especially in psoriasis lesions." (PMID 33643287, 2020). "Targeted deletion of S100A9 reduced the inflammatory phenotype of psoriasis-like inflammation in mice." (PMID 33643287, 2020). "We next analyzed the expression patterns of S100A8 and S100A9 in 25 paired samples of psoriasis treated with IL-17 directed therapy (700 mg of brodalumab) or placebo (GEO accession ID GSE53552)." (PMID 33643287, 2020). "Our data confirmed several proteins already known to be associated with psoriasis, including S100A7, S100A9, beta-defensin 3(DEFB103A), Elafin (PI3), serine protease inhibitors B3, and B4." (PMID 32849499, 2020). "The general relevance of S100A8/S100A9 expression during psoriasis is confirmed by the fact that inflammation in psoriasis-like skin disease in mice is strongly attenuated after deletion of the S100A9 gene in mice." (PMID 33643287, 2020). "Serum concentrations of S100A8/S100A9 are a reliable biomarker for monitoring disease activity in psoriasis but also rheumatoid arthritis, psoriatic arthritis or infections underlining their clinical relevance." (PMID 33643287, 2020). "Several S100 proteins and particularly S100A8 and S100A9 are highly upregulated in psoriasis plaques." (PMID 30865695, 2019). "This is the reason why S100A8 and S100A9 are strong protein candidates for therapeutic targeting of psoriasis and PsA." (PMID 31275060, 2019). "S100A8 and S100A9 proteins are highly upregulated in patients with psoriasis and have been proposed as potential biomarkers for psoriasis." (PMID 30865695, 2019). "S100A8 and S100A9 are exceedingly upregulated in the epidermis in lesional skin of patients with psoriasis and histopathological analysis of psoriatic lesions show increased levels of S100A8/A9 in keratinocytes compared to healthy skin." (PMID 30865695, 2019). "Several genes reported to be involved in psoriasis pathogenesis including S100A9, S100A8, PTPN22, PTPN6, LAMA4, IL1B and IL12RA were involved in many of these enriched biological processes." (PMID 30092825, 2018). "Top up-regulated DEGs in CP vs C include previously identified psoriasis-associated genes such as IL36A/G, SPRR2A/B/F, SERPINB4, S100A7A, S100A9, and IL17F while top down-regulated DEGs include SERTM1, IL6, and ADAMTS16." (PMID 30054515, 2018). "Moderate to severe psoriasis (PASI ≥ 12) was associated with higher S100A9 and CXCL1 expression levels in seemingly healthy skin than in patients with mild psoriasis (PASI < 12)." (PMID 28790368, 2017).